BRAF (B-Raf proto-oncogene, serine/threonine kinase)
Diseases named in the same sentence as BRAF in open-access papers (continued):
Sharing a sentence is not in itself a finding about the gene and the disease.
glioma (continued). "Our findings demonstrate the critical role of RAS-ERK signaling reactivation in driving resistance to BRAF inhibition in glioma and demonstrate the potential utility of adding SHP2 inhibitors to overcome resistance." (PMID 40900823, 2025). "First, to investigate the role of SHP2 in BRAF V600E glioma, we transiently reduced SHP2 expression in BRAF V600E glioma cells using pooled siRNA targeting PTPN11." (PMID 40900823, 2025). "Aberrations in BRAF are present in both low- and high-grade gliomas resulting in constitutive activation of the kinase." (PMID 40860828, 2025). "We next evaluated the impact of the small molecule SHP2i, TNO155, in BRAF V600E mutant glioma cell lines." (PMID 40900823, 2025). "The recent successes of BRAF/MEK combination therapy in glioma and the paucity of other effective therapies have shifted attention to understanding and overcoming therapeutic resistance." (PMID 40900823, 2025). "BRAF-mutant gliomas can be targeted therapeutically using BRAF-selective inhibitors, yet responses are often transient due to adaptive resistance through reactivation of RAS-ERK signaling." (PMID 40900823, 2025). "Selumetinib has shown clinical benefit in phase -1 and phase -2 clinical trials of recurrent and refractory pediatric low-grade gliomas with BRAF aberrations." (PMID 40094009, 2025). "Additionally, IDH mutations often co‐occur with glioma‐associated genetic alterations including BRAF, TERT promoter, 1p/19q co‐deletion, and MGMT promoter methylation, which may also result in shifts of metabolic pathways and the spatial heterogeneity of H2O2/GSH ratio." (PMID 40171868, 2025). "Pediatric low‐grade gliomas are common brain tumors often driven by MAPK pathway alterations, including rare BRAF mutations." (PMID 40765221, 2025). "Overall, our study elucidates the functional role of SHP2 in adaptive resistance to BRAFi in gliomas and highlights the therapeutic potential of combined BRAF and SHP2 inhibition for preventing or overcoming resistance." (PMID 40900823, 2025). "For example, distinguishing BRAF fusion positive diffuse low-grade glioma from more aggressive infant-type hemispheric gliomas with RTK fusions." (PMID 41487568, 2025). "In conclusion, this retrospective study provides valuable insights into the prevalence and prognostic impact of BRAF V600E mutation and CDKN2A deletion in pediatric high-grade glioma." (PMID 40860828, 2025). "To assess the in vivo effects of combined BRAFi with SHP2i, we utilized heterotopic (flank) xenografts from two BRAF V600E mutant glioma cell-line models and one patient-derived xenograft (PDX)." (PMID 40900823, 2025). "In this study, we analyzed circulating tumor DNA (ctDNA) from 78 liquid biopsies (plasma n = 44, cerebrospinal fluid n = 34 (CSF)) of 35 glioma patients, determining H3F3A K28M (K27M) and BRAF V600E mutation allele frequency using droplet digital PCR (ddPCR)." (PMID 39751690, 2025). "This combination demonstrates potent anti-tumor efficacy in vitro and in vivo, providing a promising strategy for overcoming resistance and improving outcomes in patients with BRAF V600E mutant gliomas." (PMID 40900823, 2025). "Here, we evaluate the role of SHP2, a central regulator of RAS activity, and SHP2 inhibitors in overcoming resistance to BRAF inhibitors in glioma." (PMID 40900823, 2025). "BRAF V600E has also been described in pediatric high-grade glioma but in a very low percentage of cases." (PMID 40175630, 2025). "Selumetinib has subsequently been shown to have clinical activity in children with low-grade glioma whose tumors have BRAF gene alterations." (PMID 39510293, 2024). "These rare BRAF fusions have been reported in grade 2 and 3 pleomorphic xanthoastrocytoma, pilocytic astrocytoma and low-grade glial/glioneuronal tumors, not otherwise specified (NOS), and constitute a small minority of all BRAF-fused gliomas." (PMID 39409964, 2024).
glioma (continued). "Combined therapy of BRAF p.V600E-mutant pediatric low-grade glioma with type I BRAF inhibitor and MEK inhibitor has been approved." (PMID 38779936, 2024). "We suggest that most patients with BRAF V600E gliomas should be treated with BRAFis ± MEKis upfront." (PMID 39057171, 2024). "Best response of pediatric low-grade glioma patients (based on RAPNO criteria) receiving BRAF inhibition monotherapy at Children’s Healthcare of Atlanta." (PMID 39839763, 2024). "In a recent study digital droplet PCR (ddPCR) detected BRAF V600 E alterations in 60% baseline samples of cf DNA in plasma of patients with high grade gliomas." (PMID 39634188, 2024). "We retrospectively reviewed our Jordanian experience of using compassionate BRAF/MEK inhibitors in treating children with gliomas." (PMID 39399174, 2024). "Upregulation of ETS transcription factors involved in the reactivation of telomerase can diminish the efficacy of BRAF inhibitors in patients with BRAF-mutant pediatric gliomas." (PMID 38431573, 2024). "While Trametinib and Dabrafenib have shown potential in treating BRAF-mutant gliomas, the development of reliable predictive biomarkers remains critical." (PMID 39654184, 2024). "When compared with classic DMG, H3K27-altered, survival also tends to be longer (median OS of 37 and 36 months in BRAF-altered and FGFR1-altered H3K27M gliomas, versus 12 months of median OS in BRAF- and FGFR1-wildtype H3K27M gliomas)." (PMID 39126064, 2024). "We report for the first time on a series of children with gliomas treated with BRAF/MEK inhibitors in a resource-limited country." (PMID 39399174, 2024). "Structural rearrangements of BRAF also represent a potentially actionable subgroup of BRAF alterations and are most prevalent in gliomas, prostate cancers and pancreatic cancers." (PMID 39018217, 2024). "MAPK-driven included PAs with BRAF alterations (BRAFV600E, n = 30; BRAF fusion, n = 38; BRAF MT other, n = 20), diffuse low-grade gliomas with MAPK alterations (n = 1), and rosette-forming glioneuronal tumors (n = 7)." (PMID 39137048, 2024). "Future research should focus on identifying and validating specific biomarkers that can accurately predict patient responses to Trametinib and Dabrafenib in pediatric BRAF-mutant gliomas." (PMID 39654184, 2024). "This study aimed to evaluate the effects of dabrafenib and/or trametinib therapy in BRAF v600-mutant glioma treatment." (PMID 39172230, 2024). "The combination of dabrafenib (a BRAF inhibitor) and trametinib (a MEK inhibitor) has been studied extensively in various cancers, including pediatric gliomas with BRAF mutations." (PMID 39654184, 2024). "Combination therapy with Dabrafenib, a BRAF kinase inhibitor, and Trametinib, a MEK inhibitor, has shown significant improvement in overall survival and progression-free survival for pediatric patients with BRAF V600-mutant gliomas." (PMID 39654184, 2024). "Mutations in IDH, PTEN, 1p/19g, TERT, ATRX, BRAF, and H3F3A in gliomas are of great significance for patient prediction and prognosis." (PMID 39206155, 2024). "In this issue, Rajappa and colleagues leverage a novel immunocompetent RCAS-BRAF V600E murine glioma model to profile the immunological dynamics taking place in BRAF V600E pLGG." (PMID 39188362, 2024). "One promising option is vemurafenib, a highly selective BRAF V600 inhibitor that has demonstrated long-term antitumor effects in some patients with BRAF V600 mutant gliomas." (PMID 39484048, 2024). "The identification of predictive biomarkers will significantly advance the management of pediatric BRAF-mutant gliomas, enabling the implementation of personalized medicine strategies that tailor interventions to individual patient profiles." (PMID 39654184, 2024). "Care should be taken in generalizing this OS too broadly as our population had 3 IDH-mutant gliomas, and one who had a silent IDH mutation, BRAF and three-year survival, suggesting the possibility of alternative pathology such as epithelioid GBM or PXA." (PMID 39112464, 2024).
glioma (continued). "In low-grade gliomas we identify distinct patterns of immune activation with prognostic significance in BRAF V600E-mutant tumors." (PMID 38987542, 2024). "Given that no clinical trial has been able to address these critical questions, we developed a Canadian Consensus statement for the treatment of BRAF V600E mutated pediatric as well as adolescent and young adult (AYA) gliomas." (PMID 39057171, 2024). "This trial specifically focuses on determining the extent of autophagy inhibition and its correlation with resistance profiles of gliomas, as well as the specific involvement of autophagic processes in the context of BRAF anomalies." (PMID 39184045, 2024). "Multiple case reports have shown some clinical efficacy of BRAF inhibitors (vemurafenib, dabrafenib) either alone or in combination with MEK inhibitors (trametinib) in BRAF-mutated glioma patients." (PMID 38203795, 2024). "Glioneuronal tumors, high-grade gliomas, and pilocytic astrocytomas had the highest match rates at 89%, 70%, and 64%, respectively, driven by BRAF alterations." (PMID 38992034, 2024). "Based on expert consensus in Canada, we developed both an algorithm for the initiation of treatment for children and AYA with BRAF V600E gliomas as well as a discontinuation of the treatment algorithm." (PMID 39057171, 2024). "Mitogen-activated protein kinase kinase (MEK) inhibitors appear to be effective therapies for KIAA1459::BRAF-driven pediatric low grade gliomas, reducing tumor growth and improving survival." (PMID 37221626, 2023). "Further work is necessary to prospectively validate outcomes and identify the role of other BRAF alterations in patients with glioma." (PMID 36854806, 2023). "By contrast, low-grade gliomas, especially pilocytic astrocytomas, predominated in pediatric BRAF-altered cases (p = 0.0003)." (PMID 36854806, 2023). "In patients with targetable alterations (Class I–III), small molecule inhibitors can have a significant clinical benefit, underscoring the importance of accurately identifying and classifying BRAF alterations in patients of all ages with glioma." (PMID 36854806, 2023). "A small cluster (Cluster 3) of primarily high-grade gliomas contained mostly unclassified BRAF alterations." (PMID 36854806, 2023). "Trametinib is currently in clinical trials for the treatment of refractory low-grade gliomas and plexiform neurofibromas and has been approved for adult BRAF V600E mutant cancers." (PMID 37726268, 2023). "Although BRAF alterations and targeting are the focus of this paper, other ERK/MAPK pathway alterations are implicated in glioma, due to their common downstream effects and the possibility of combined therapeutic targets." (PMID 37124503, 2023). "The phase II VE-BASKET study includes single-agent vemurafenib in patients with recurrent BRAF V600E–mutant cancers including gliomas." (PMID 37124503, 2023). "Some alterations such as CDKN2A/B loss, PTEN, EGFR, NF1, and TERT promoter mutations have been shown to be associated with very poor clinical outcomes in patients with BRAF-altered gliomas." (PMID 37920169, 2023). "The combination of BRAF-mutant and MEK inhibitors has shown some clinical efficacy in BRAF-mutant gliomas." (PMID 37325516, 2023). "Although BRAF has been subject to much interest in gliomas, multiple other pathway alterations are observed across cancer subtypes, with relevance to treatment." (PMID 37124503, 2023). "Third, the spectrum of BRAF alterations is different between pediatric and adult glioma, with important ramifications for clinical outcomes." (PMID 36854806, 2023). "Though ion-channel dysfunction was strongly implicated in such observations, how ion channels specifically function in BRAF glioma progression currently remained unclear." (PMID 36763212, 2023).
glioma (continued). "The concept emerged notably in experiments focusing on neural stem cells where fusion involving BRAF gene induced only low-grade glioma-like lesions after engraftments." (PMID 36831610, 2023). "While the most common SNV in BRAF was at p.V600E in both adult and pediatric gliomas, alterations at other sites known to affect BRAF dimerization or increase ERK signaling (Class II/III) were more common in adult samples." (PMID 36854806, 2023). "We observed that adult and pediatric BRAF-mutant gliomas harbor distinct clinical and molecular features, with a higher prevalence of BRAFV600E (Class I) and BRAF fusions in pediatric tumors." (PMID 36854806, 2023). "Early studies of BRAF inhibitors as monotherapy and, more recently, in combination treatment have shown encouraging results in gliomas." (PMID 37124503, 2023). "As BRAF and FGFR1 mutations are typical hallmarks of low-grade gliomas/glioneuronal tumours such as ganglioglioma or pilocytic astrocytoma, the co-occurrence of H3-K27 and these MAPK alterations makes diagnosis and grading difficult." (PMID 38066305, 2023). "The more potent allosteric MEKi trametinib is approved for adult BRAF V600E mutant cancers and is also currently undergoing evaluation in both refractory low-grade gliomas and plexiform neurofibromas (NCT03363217, NCT02124772)." (PMID 37726268, 2023). "This landscape of BRAF alterations in adult glioma provides an invaluable resource to clinicians evaluating the functional implications of various BRAF alterations in adults with glioma." (PMID 36854806, 2023). "Western Blot with a specific anti-p-BRAF showed that the level of p-BRAF was significantly higher in DBTRG-05MG cells than that in two control glioma cell lines." (PMID 36763212, 2023). "Clinical trials of dimer-disrupting BRAF inhibitors with potential efficacy in additional BRAF-altered classes are ongoing in adults with glioma (NCT05503797)." (PMID 36854806, 2023). "These successes have prompted further understanding of the role of BRAF alterations in tumorigenesis and as a therapeutic target in gliomas." (PMID 37124503, 2023). "Targeting oncogenic drivers is already a cornerstone of treatment for a subset of glioma patients, most notably those with Neurofibromatosis 1 (NF1) mutations, BRAF fusions and BRAFV600E mutated LGG and HGG." (PMID 37781183, 2023). "All those sparse observations are in favor of the early involvement of the AKT/mTor pathway in BRAF-mutant glioma development." (PMID 36831610, 2023). "Nevertheless, little is known about the associated biomarkers involved potentially in gliomagenesis modifications or acceleration and therapeutic resistances along the patient journey with BRAF-altered gliomas." (PMID 36831610, 2023). "This review will summarize the up-to-date literature regarding BRAF-altered gliomas, their molecular diagnosis, their prognosis, their associated molecular alterations, and how potentially treat those tumors." (PMID 36831610, 2023). "Overall, this large cohort of BRAF-altered adult gliomas demonstrates a broad range of molecular alterations with implications for treatment sensitivity and survival." (PMID 36854806, 2023). "When adults with rearrangements were separated by grade, there was a survival difference between grade 1 and grade 4 gliomas, suggesting grade serves as a more accurate prognostic indicator than the presence of a BRAF rearrangement alone." (PMID 36854806, 2023). "Similar mutual regulations of p-BRAF and KCNMA1 levels were then recapitulated in human glioma cells with the BRAF mutation." (PMID 36763212, 2023). "In the glioma cell line, p-BRAF activated downstream signaling pathways accompanied by higher KCNMA1 expression." (PMID 36763212, 2023). "For CPTAC, clinical annotations included diagnosis (we excluded diagnoses other than ganglioglioma and other low grade glioma), extent of resection, BRAF status, tumor grade, EFS, and death." (PMID 36966348, 2023).
glioma (continued). "We obtained clinical and molecular data from 296 patients with BRAF-altered glioma (151 males, 145 females), including 206 adults (median 43 years, range 18–85 years) and 90 children (age <18 years, median 10 years, range 0–17 years)." (PMID 36854806, 2023). "The BRAF inhibitors dabrafenib and vemurafenib have demonstrated clinical efficacy in patients with gliomas, despite being substrates for efflux pumps." (PMID 38143440, 2023). "Another study used patient-derived glioma tissue from paired pre-/post- BRAF/MEK inhibitor treatment to identify treatment-related changes in gene alterations and expression using RNA and DNA sequencing." (PMID 37920169, 2023). "Even though patients with NF1 low-grade gliomas share the same tumor pathways with BRAF V600-mutant low-grade gliomas, the administration of these drugs is still mostly limited to clinical trials or off-label use." (PMID 38139220, 2023). "In pediatric gliomas, specific genetic alterations are more commonly seen, such as BRAF fusion or mutation, KIAA1549-BRAF fusion, and mutations in histone genes (H3F3A or HIST1H3B)." (PMID 37444408, 2023). "Radiographic partial response was also noted in two patients with BRAF V600E-mutant high-grade glioma who were treated with dabrafenib and trametinib." (PMID 38143440, 2023). "The co-dependency and mutual regulation of KCNMA1 and p-BRAF levels seems to be therefore confirmed for BRAFV600E glioma cells in a human context." (PMID 36763212, 2023). "Recently, the first published phase II clinical trial for dabrafenib/trametinib treatment in BRAF V600E-mutant glioma patients, conducted across 27 institutes, described an overall objective response rate of 32% in glioblastoma patients." (PMID 37857607, 2023). "Compared to other BRAF-altered gliomas, tumors with Class I alterations had elevated expression of several well-known tumor microenvironment marker genes." (PMID 36854806, 2023). "This set of APXA models will serve as a preclinical resource for developing novel therapeutic regimens for rare anaplastic PXAs and pediatric high-grade gliomas bearing BRAF fusions." (PMID 37280243, 2023). "According to the European Association of Neuro-Oncology (EANO), treatment with RAF-kinase inhibitors such as dabrafenib is recommended for patients with progressive gliomas that have BRAF-V600E alterations." (PMID 38275375, 2023). "This downregulation is also frequently present in BRAF p.V600E gliomas, such as anaplastic forms or in pediatric diffuse MAPK-altered gliomas, GGLs and PXAs." (PMID 36831610, 2023). "After BRAF alterations, NF1 mutations are the next common MAPK changes, at approximately 15% of all gliomas." (PMID 37124503, 2023). "Other variants, such as IDH2, BRAF, and PIK3A, had low-frequency and were mainly present in patients with other gliomas, while low-frequency EGFR variants were more common in GBM patients." (PMID 36959606, 2023). "This demonstrates that elevated Slo expression is required for BRAF/MAPK pathway activation in dRafGOF gliomas and that the knockdown of slo reduces p-MEK and p-ERK levels." (PMID 36763212, 2023). "Out of these cases (15 tumors groups), BRAF fusions are most identified in glioma (29.5%), melanoma (23%), lung carcinoma (11.5%) and colorectal carcinoma (6.6%) 4,26,27." (PMID 37280243, 2023). "An ongoing large multicenter basket clinical trial has tested the combination of dabrafenib and trametinib in adults with recurrent or progressive BRAF V600–mutant gliomas (NCT02034110)." (PMID 37124503, 2023). "Another nuance to the role of BRAF alterations in glioma prognosis is the broad range of alterations present in adult glioma." (PMID 36854806, 2023).